CNTNAP2 (contactin associated protein 2)
Diseases named in the same sentence as CNTNAP2 in open-access papers (continued):
Sharing a sentence is not in itself a finding about the gene and the disease.
autism (continued). "To determine whether changes in CNTNAP2 expression levels occur in the cortex in autism, we developed a quantitative RT-PCR assay with amplification conditions optimized to allow efficiencies of 1.0 ± 0.05." (PMID 24147096, 2013). "An independent analysis of children with SLI, but not autism, identified association of CNTNAP2 variants with lower levels of language ability." (PMID 23176600, 2012). "Furthermore, CNTNAP2, one of the SNPs whose expression is regulated by FOXP2, is associated with impairments of language development in several syndromes, such as autism and SLI." (PMID 23115634, 2012). "Independent analyses of children with specific language impairment (SLI), but not autism, identified association of CNTNAP2 variants with reduced performance on quantitative indices of language ability." (PMID 21310003, 2011). "Although these conditions are generally regarded as quite distinct, the boundaries between them can be hard to draw, and it has been suggested that there is some genetic overlap, with variants of the CNTNAP2 neurexin gene being associated with both SLI and autism." (PMID 21418292, 2011). "It follows that CNTNAP2 variation is not ‘the cause’ of SLI or autism, but rather acts as a risk factor that leads to clinically significant impairment only when it occurs in conjunction with other risk factors." (PMID 21418292, 2011). "Our hypothesis was that the particular CNTNAP2 markers implicated in language impairments of SLI and delayed language in autism would extend their influence beyond disorder, to show association with early language acquisition in the general population." (PMID 21310003, 2011). "Moreover, a number of publications have demonstrated the relevance of particular genes to ASD, and numerous candidate genes for autism have been identified, including NLGN3/4, SHANK3, NRXN1, and CNTNAP2 (Contactin associated protein-like 2)." (PMID 20374639, 2010). "CNTNAP2 has been identified as a candidate gene for autism, and heterozygous deletions involving the gene were reported in three patients with schizophrenia and autism." (PMID 20502679, 2010). "Another gene in the contactin family, CNTNAP2, is found to be mutated in the Amish population causing a rare neuronal migration disorder, cortical dysplasia-focal epilepsy (CDFE), resulting in language delay, seizures and autism." (PMID 20345892, 2010). "In addition, increasing the excitability of prefrontal PV interneurons using optogenetic approaches rescued deficits in social behavior in mice lacking the autism-linked gene CNTNAP2." (PMID 39406516, 2024). "Furthermore, ASD-associated pathogenic CNTNAP2 mutations inhibited the α-cleavage, leading to autism-like phenotypes in vivo, whereas exogenous expression of the α-cleavage product C79 improves autism-like phenotypes in the Cntnap2-I1254T knock-in and Cntnap2−/− knockout mice." (PMID 38424048, 2024). "A family-based association study suggested that CNTNAP2 polymorphisms might not be associated with autism." (PMID 35628852, 2022). "Among them, CNTNAP2, a cell adhesion molecule associated with autism is observed in 7 of the 18 non‐diagnosed control pineal glands and absent of the 7 pineal glands from the individuals with autism." (PMID 33368564, 2021). "Indeed, several large DNA deletions affecting one of the two copies of CNTNAP2 were found in some patients with autism, and later also in patients with schizophrenia, bipolar disorder, ADHD and epilepsy, suggesting that this gene was implicated in several psychiatric or neurologic diseases." (PMID 30586385, 2018). "Interestingly, a recessive non-coding mutation for CNTNAP2 causes cortical dysplasia focal epilepsy syndrome (CDFE), characterised by seizures, intellectual disability, hyperactivity, and in two-thirds of cases, autism." (PMID 25491076, 2015).
autism (continued). "Whether this altered expression is caused by cis-acting or trans-acting factors in the CNTNAP2 locus was not resolved in this study, nor whether low or high expression might be deleterious, advantageous, or benign, with respect to the autism phenotype." (PMID 24147096, 2013). "The CNTNAP2 gene, as well as other candidate risk genes for autism, might not be identified in a case-only analysis of our study." (PMID 23977206, 2013). "As this gene is related to CNTNAP2, it was sequenced in additional ASD families from the International Molecular Genetic Study of Autism Consortium (IMGSAC) cohort to search for other rare variants that might be of etiological relevance to autism." (PMID 20346443, 2010). "Thus, genetic variants of CNTNAP2 might predict which individuals with SCT have SLI and/or autism." (PMID 21418292, 2011). "The identification of novel rare CNVs in autism (NRXN1, SHANK3, and CNTNAP2) and schizophrenia has generated much excitement." (PMID 21209939, 2010). "This provides a benefit over conspecific stimuli, which has a social component and is therefore not ideal for a study of autism given that Cntnap2 knockout rodents exhibit abnormal social behavior and vocalizations." (PMID 40824873, 2025). "Notably, 22 out of the 45 reported (candidate) genes are known to be related to a broader phenotype than DLD, including intellectual disability, epilepsy, and/or autism (e.g., GRIN2A, CNTNAP2, CNTNAP5, AUTS2)." (PMID 38298611, 2024). "Several studies have found that Tau reduction prevents autism-like phenotypes in Scn1aRX/+ and Cntnap2−/− mice but not in Shank3B−/− mice." (PMID 37936174, 2023). "Despite the previous consideration of CNTNAP2 as a strong candidate gene for autism or schizophrenia, we show little evidence across multiple classes of DNA variation, that CNTNAP2 is likely to play a major role in risk of psychiatric diseases." (PMID 30586385, 2018). "Moreover, several genetic overlaps between SLI, autism and ADHD have been observed, the most prominent of which is the implication of the CNTNAP2 gene in all three disorders." (PMID 24571439, 2014). "Although previous studies have suggested that tau reduction prevents key features of autism in Cntnap2–/– and Scn1aRX/+ mice, this may not contradict our findings." (PMID 36474209, 2022). "Further studies are needed to understand if and how OT may regulate social interactions and other relevant behaviours in zebrafish mutants lacking CNTNAP2, SHANK3, and other genes contributing to the risk of autism." (PMID 32214126, 2020). "Notably, findings implicating CNTNAP2 in both autism and language impairment without autism suggest distinct CNTNAP2 pathways for verbal trait disorders, including CAS." (PMID 24083349, 2013). "Our findings recall the observation that men are identified as being on the autism spectrum four times as often as women, and would be consistent with the possibility that regulation of some genes (by our measures, Cntnap2) but not others (Tsc1) might have differential effects by sex." (PMID 35279205, 2022). "However, the expression of C79 significantly reduced the number of no alterations of Cntnap2-I1254T mice in T maze test and increased their social interactions with unfamiliar mice at the age of 7 weeks, indicating that C79 expression improved autism-like phenotypes in the mutant mice." (PMID 38424048, 2024). "By contrast, most studies on rodent models of autism found no change in ABR P1 waves or latencies, except for late waves in Cntnap2 Fragile X syndrome models, and, even then, only in young individuals." (PMID 38002499, 2023).
autism (continued). "Recently, the Autism Mouse Connectome (AMC) study compared connectivity alterations in 16 autism-related genetic and etiological models including Cntnap2 and Shank3 knockout models, but not Nrxn1." (PMID 35052369, 2021).
encephalitis (162 papers, 2013 to 2026). An acute inflammatory process affecting the brain parenchyma. "Anti‐contactin‐associated protein 2 (anti‐CASPR2) encephalitis is characterized by a long course of the disease." (PMID 39315845, 2024). "CSF examination was available in 13 patients and showed lymphocytic pleocytosis in 2 patients: 1 with anti-contactin-associated protein 2 (anti-Caspr2) antibody encephalitis and 1 with meningo-polyradiculitis." (PMID 32734353, 2021). "We report a case presenting with serial changes in blood cytokine levels in a male patient with anti-contactin-associated protein 2 (Caspr2) encephalitis." (PMID 32791989, 2020). "Cerebellar ataxia is also one of the core symptoms of Contactin-associated-protein-2 (CASPR2)-antibody associated encephalitis and is seen in up to a third of patients." (PMID 33324912, 2020). "It is important to differentiate anti-contactin-associated protein-2 (CASPR2) encephalitis from motor neuron diseases." (PMID 30233481, 2018). "However, there are few reports of anti-contactin-associated protein-2 (CASPR2)-related encephalitis, especially with positive anti-aquaporin 4 (AQP4) antibodies." (PMID 37335713, 2023). "However, morvan syndrome is the main feature of anti-contactin-associated protein 2 (CASPR2) encephalitis." (PMID 35778696, 2022). "However, disease-specific variations, such as complement activation in anti- contactin-associated protein 2 (Caspr2) encephalitis but not in other types of surface-antigen-associated autoimmune encephalitis, cannot be neglected." (PMID 32791989, 2020).
epilepsy (93 papers, 2010 to 2025). A brain disorder characterized by episodes of abnormally increased neuronal discharge resulting in transient episodes of sensory or motor neurological dysfunction, or psychic dysfunction. "Here it is worth noting that the epilepsy associated with focal cortical dysplasia and Cntnap2 mutations is commonly resistant to pharmacological management and new treatments are urgently needed." (PMID 41408339, 2025). "CNTNAP2 genetic variations have been implicated in multiple neurodevelopmental disorders including schizophrenia, epilepsy, autism spectrum disorder, attention-deficit/hyperactivity disorder, and mental retardation." (PMID 38052982, 2024). "Our results provide evidence of a bilateral independent anatomoelectroclinical involvement of the temporal lobes in CNTNAP2‐associated epilepsy, which negatively affects surgical treatment options and the overall epilepsy outcome." (PMID 37805811, 2024). "In one study, a missense CNTNAP2 variant was identified in two consanguineous Pakistani families with epilepsy, DD, ID, and aggressive behavior." (PMID 38783254, 2024). "We have defined the main features associated with biallelic CNTNAP2 variants, as severe cognitive impairment, epilepsy and behavioral abnormalities." (PMID 37183190, 2023). "They over-expressed CNTNAP2 p.R777G, a mutation associated with intellectual disability and epilepsy, in mouse cortical neurons." (PMID 36340692, 2022). "First, our group investigated the ASD and epilepsy risk gene, Contactin Associated Protein-like 2 (CNTNAP2), and identified estrogenic compounds in an unbiased screen as a suppressor of a behavioral phenotype in zebrafish lacking the function of this gene." (PMID 34690830, 2021). "CNTNAP2 has been considered a prominent disease susceptibility gene associated with epilepsy, and seizure was observed in Cntnap2 knockout rat." (PMID 34956060, 2021). "Heterozygous variants in CNTNAP2 have been implicated in a wide range of neurological phenotypes, including intellectual disability (ID), epilepsy, autistic spectrum disorder (ASD), and impaired language." (PMID 34641913, 2021). "CNTNAP2, a protein belonging to the pre-synaptic cell-adhesion protein family neurexin, is associated with many neurological disorders, including epilepsy." (PMID 34296100, 2020). "A wide variety of intronic variants of CNTNAP2 gene has been reported in patients with severe ID, autistic behavior, epilepsy, and breathing anomalies that phenotypically overlap with PTHS." (PMID 33042910, 2020). "ASD patients carrying rare functional variants of CNTNAP2 or MEF2C were more likely to have epilepsy/tics and require monitoring of these comorbidities." (PMID 30763456, 2019). "CASPR2 is clearly important in neuronal migration, as highlighted by the occurrence of cortical dysplasia in patients with an autism spectrum disorder and epilepsy due to CNTNAP2 (the gene encoding for CASPR2) homozygous mutations." (PMID 28755208, 2017). "Mutations in CNTN2 and CNTNAP2 (the genes encoding contactin-2 and Caspr2, respectively) have been identified in autism spectrum disorder, epilepsy, Tourette’s syndrome, schizophrenia and ADHD." (PMID 24913350, 2014). "Like PRICKLE1, SYN1 and CNTNAP2 were also initially identified as epilepsy genes, but later studies associated them with ASDs." (PMID 24312498, 2013). "Our study expands the phenotypic and genetic spectrum of biallelic CNTNAP2 alterations providing clear evidence for an elective bilateral anatomoelectroclinical involvement of the temporal lobes in the associated epilepsy, with relevant implications on clinical management." (PMID 37805811, 2024). "Epilepsy is indeed a cardinal feature in patients with biallelic CNTNAP2 variants." (PMID 37183190, 2023). "Furthermore, as a susceptible gene of epilepsy, CNTNAP2 mutation or deletion results in the break of E/I balance in neuronal network." (PMID 34737720, 2021).
epilepsy (continued). "Additionally, CNTNAP2 mutations are linked to ADHD as well as epilepsy and seizures, conditions that are commonly co-morbid with ASD." (PMID 29209173, 2017). "Moreover, Par3 may indirectly contribute to epileptogenesis through CNTNAP2, which has been considered a prominent disease susceptibility gene associated with epilepsy." (PMID 34956060, 2021). "Contactin associated protein-like 2 knockout (Cntnap2 KO) mice, a model of ASD and epilepsy, exhibit sleep and circadian disturbances and abnormal events in the electroencephalogram (EEG)." (PMID 41408339, 2025). "Using epilepsy panels and WES, we identified rare variants in several genes, including POLG, SCN1A, SCN9A, KIF1A, and CNTNAP2, which were associated with specific clinical characteristics." (PMID 40565516, 2025). "Our findings provide a further example of management strategies driven by genetic diagnosis, that is, surgical treatment would seem to be unsuccessful in patients with CNTNAP2‐related epilepsy." (PMID 37805811, 2024). "Recently, homozygous variants in OCLN, ALDH7A1, IQSEC2, COL3A1, CNTNAP2, TRIT1, and NARS1 were identified in individuals from Pakistani families who presented with epilepsy and frequently accompanied DD phenotype." (PMID 38783254, 2024). "Mutations in the contactin-associated protein-like 2 (CNTNAP2) are implicated in cortical dysplasia-focal epilepsy syndrome, epilepsy, attention-deficit hyperactivity disorder and autism spectrum disorders." (PMID 36816855, 2023). "Homozygous loss-of-function mutation in contactin-associated-protein-like 2 (CNTNAP2) causes a special kind of ASD, with the symptoms of early-onset epilepsy and increased head circumference." (PMID 35846370, 2022). "CNTNAP2 has been confirmed to be involved in several nervous system diseases including epilepsy, ASD, schizophrenia, language difficulties, and intellectual disability." (PMID 34737720, 2021). "CNTNAP2 was first implicated in the cortical dysplasia-focal epilepsy (CDFE) syndrome, a recessive disease characterized by intellectual disability, epilepsy, language impairments and autistic features." (PMID 30586385, 2018). "Missense heterozygous mutations in the contactin-associated protein-like 2 (CNTNAP2) are implicated in cortical dysplasia-focal epilepsy (CFDE) syndrome and are associated with epilepsy, seizures, attention-deficit hyperactivity disorder (ADHD) and ASD." (PMID 29970997, 2018). "In a cohort of Amish children, mutations within contactin-associated protein-like 2 gene (CNTNAP2) were found to be implicated in ASD and epilepsy." (PMID 29209173, 2017). "Recent studies have shown that several SNPs of CNTNAP2 are biological high-risk markers in ASD, epilepsy, mental retardation, schizophrenia, and cognitive impairment." (PMID 25941478, 2015). "Patients with such mutations may only have ASD, in contrast, the patients with CNTNAP2 gene deletion have both ASD and epilepsy." (PMID 37271769, 2023). "The protein CNTNAP2 mutation is associated with both ASD and epilepsy." (PMID 36819340, 2023). "This evidence is in line with several studies carried out in several experimental models of ASD-epilepsy (Cntnap2, En2, Fmr1, Nrp2), in which defects of GABAA receptor-mediated neurotransmission have been related to the pathogenesis of ASD-epilepsy comorbidity." (PMID 37153775, 2023). "Additionally, homozygous deletions of various sizes within CNTNAP2 have also been identified in patients with epilepsy, intellectual disability and/or autism spectrum disorder." (PMID 35911904, 2022). "Also suggestive of their functional role is the fact that the CNTNAP2 HARs overlap deletions associated with neurodevelopmental disorders, including ASD, SLI, ID, and epilepsy." (PMID 36340692, 2022).